CAT (catalase)
Diseases named in the same sentence as CAT in open-access papers (continued):
Sharing a sentence is not in itself a finding about the gene and the disease.
tumor (continued). "Additionally, the incorporation of hemin into the ADP provided catalase activity, converting tumor-abundant H2O2 into O2, thereby ameliorating tumor hypoxia." (PMID 38269029, 2024). "The mechanism is that the expression of catalase in the membrane of M1 macrophage-derived exosomes not only improves hypoxia in the tumor microenvironment, but also enhances DNA damage in tumor cells, and DNA damage repair inhibitors encapsulated in M1Exos can significantly limit DNA damage repair." (PMID 38595822, 2024). "Singlet oxygen from cold atmospheric plasma (CAP) or plasma-activated medium (PAM) triggers tumor cells to generate high concentrations of secondary singlet oxygen, inactivating their protective catalase and reactivating ROS/RNS-dependent apoptosis-inducing signaling." (PMID 39765910, 2024). "Additionally, 1357 proteins were identified in TV and some of them were bio-active proteins such as glucose-6-phosphate isomerase, catalase, and lysozyme C-1, which had catalytic, antioxidant, antimicrobial, and anti-tumor activities." (PMID 38535825, 2024). "The Cu‐doped polypyrrole nanozyme (CuP) with trienzyme‐like activities, including catalase (CAT), GPx, and peroxidase (POD) could also efficiently reverse immunosuppressive TME by overcoming tumor hypoxia and re‐educating tumor‐associated M2 macrophage." (PMID 38063781, 2024). "Furthermore, overexpressing the Catalase gene in RasV12DlgRNAi tumor cells we also found that both 4DP-induced CABs and tumors were strongly reduced." (PMID 38830901, 2024). "In addition, the polymer coating significantly improved the biodistribution of NanoICD/CAT, with significantly enhanced fluorescence signals observed in tumor tissues of mice treated with NanoICD/CAT-PCA compared to NanoICD/CAT." (PMID 38324678, 2024). "Use of catalase as a cancer therapeutic has been proposed to reduce oxidative stress and hypoxia in the tumor microenvironment, both activities which are hypothesized to reduce tumor growth." (PMID 37311396, 2023). "Hence, CAT-based polymer-protein systems have been developed to protect CAT from protease digestion during circulation to enable efficient delivery to tumor sites." (PMID 37177365, 2023). "Also, the modification of the shell using the catalase helped in avoiding the occurrence of hypoxia, as the catalase converts the H2O2 formed in the tumour cells into oxygen." (PMID 38112849, 2023). "The antioxidant status of liver and pancreas tumor cell lines, incubated with pepper fruit extracts from Alegría riojana, was then analyzed, and the activity profile of catalase, superoxide dismutase, glutathione peroxidase, and several NADPH-generating enzyme systems was determined." (PMID 37507999, 2023). "Moreover, Pt endowed with the catalytic property of CAT modulates the engagement of O2 to alleviate tumor hypoxia and boost sonodynamic-therapy-induced ROS production." (PMID 37259396, 2023). "Based on this dual activity of ROS, catalase may play a dichotomous role in cancer, acting to suppress or promote tumor growth and metastasis depending on the metabolic landscape and redox status of cancer cells." (PMID 37311396, 2023). "Catalase may exert differential effects on tumor growth and metastasis depending on the balance of pro- and anti-tumorigenic activities of hydrogen peroxide in cancer cells within the tumor." (PMID 37311396, 2023). "While anchoring to alum robustly enhances retention of catalase activity in the tumor, it may result in an uneven distribution." (PMID 37311396, 2023). "Therefore, integrating CAT and MnO2 into bionanoreactors provides an attractive nanotechnological route to effectively enhance tumor therapy." (PMID 36703877, 2023). "During the in vivo intravesical experiment, the fluorescence detection indicated that CAT-TCPP/FCS NPs possesses an excellent transmucosal absorption capacity and the combination with FCS significantly enhanced the penetration of CAT-TCPP into the interior of the tumor tissue." (PMID 36671940, 2023).
tumor (continued). "Recently, researchers have developed various biomaterials and therapeutic agents to reduce tumor hypoxia, including hemoglobin, catalase (CAT), manganese dioxide NPs, oxygen shuttle nanoperfluorinated compounds (nanoPFCs), hyaluronidase (HAase), and metformin (Met)." (PMID 36900322, 2023). "Catalase may protect cells from tumor initiation and progression by preventing the accumulation of ROS." (PMID 38068888, 2023). "In contrast, Badawy, El-Magd and AlSadrah reported lower levels of the lipid peroxidation biomarker (MDA), upregulated expression of iNOS, and higher activities of antioxidant enzymes (SOD, CAT, GPx) in tumor tissues of MCF7 xenograft following treatment of rats with CM-EXOs." (PMID 36851428, 2023). "After 1 week, CAT expression in homogenized tumor lysate was measured by western blot." (PMID 37311396, 2023). "It has been reported that catalase (CAT) effectively decomposes overexpressed H2O2 in tumor tissue into oxygen to relieve tumor hypoxia, while HDACi induces histone hyperacetylation to impede the affinity of histones for DNA; thus, consequently triggering radiosensitization." (PMID 36599655, 2023). "Their expression decreases 15–30% in response to EC CAT, suggesting catalase may result in very subtle increases in tumor oxygen levels." (PMID 37311396, 2023). "This nanocarrier was loaded with catalase and metformin, which is responsible for inhibiting the mitochondrial respiration of cancer cells, reducing the activity of tumor cells, and increasing the concentration of oxygen in PDT, upon its linkage with chlorine e6 photosensitizer." (PMID 38276492, 2023). "With perfluoropolyether and catalase converged in one nanoplatform CCIPN, the oxygen generated by the decomposition of tumor-overproduced hydrogen peroxide via catalase could be reserved by perfluoropolyether for PDT." (PMID 36900370, 2023). "We found that CAT is mainly expressed within the cytoplasm of tumor cells and immune cells." (PMID 37313408, 2023). "MNDDSs loaded with catalase (CAT) or metal oxide could induce local decomposition of H2O2 to produce O2 in tumor tissues." (PMID 36945005, 2023). "In addition, intracellular zinc ions can produce ROS, further facilitated by the generated H2S gas from ZnS, which inhibits catalase under acidic TME in tumor cells." (PMID 37342347, 2023). "In addition to extracellular anchored catalase, we overexpressed intracellular catalase in tumor cell lines, with the aim of disrupting peroxide-mediated intracellular signaling." (PMID 37311396, 2023). "CAT catalyzes high levels of H2O2 at tumor sites to produce oxygen and water." (PMID 37177365, 2023). "CAT, CECR1 and GPI have all been previously associated with promoting tumor progression." (PMID 38149248, 2023). "Administration of exogenous catalase as a cancer therapeutic has been proposed to modulate the tumor microenvironment (TME) by: 1) decreasing oxidative stress by reducing the level of hydrogen peroxide and 2) decreasing hypoxia by increasing the amount of oxygen." (PMID 37311396, 2023). "Consequently, tumor-targeted delivery of CAT is essential to lower hypoxia levels, and the proteolytic degradation of CAT presents another challenge that needs to be addressed." (PMID 35624636, 2022). "Similarly, reduced inflammatory regulator NFKB1 and increased negative regulator CAT indicated that KMV stimulation prevented macrophage polarizing into inflammatory tumor suppressive phenotype, which is in line with our previous qPCR results." (PMID 36311795, 2022). "Subsequently, Ce6-CAT by repeated laser stimulation continuously generated ROS to induce strong ICD and regulate the polarization of macrophage, as the retained CAT could overcome tumor hypoxia by persistently producing O2." (PMID 34987658, 2022). "Notably, the higher level of H2O2 in the tumor region can be decomposed into oxygen in the presence of the catalase accordingly can serve as feasible origination of oxygen to remit hypoxia." (PMID 35413839, 2022).
tumor (continued). "Therefore, carriers that co-deliver CAT and photosensitizers into cells to enhance their anti-tumor effect have been developed." (PMID 36147526, 2022). "The common characteristic of tumor, such as weak acidity, insufficient catalase activity, and intolerance of external reactive oxygen species (ROS), could be found in the orthoptic liver tumor model." (PMID 35712774, 2022). "Gal-catalase (galactosylated) and Suc-catalase (succinylated), catalase derivatives, have been discovered to reduce liver surface metastasis by suppressing nuclear factor B (NF-B) activity in liver and tumor cells." (PMID 36235013, 2022). "G5’ could better inhibit tumor growth than G4’ and G3′, exhibiting the obvious radiotherapy sensitization effect of CAT and DDRi." (PMID 35715382, 2022). "While the decomposition of H2O2 by CAT could generate O2 in the TME, the poor retention ability of Ce6-CAT alleviated the tumour hypoxia status at the initial state, but it was recovered within 48 h after PDT treatment." (PMID 36277398, 2022). "In contrast, after light irradiation, the Ce6-CAT/PEGDA group showed a striking reduction in the degree of hypoxia over a period of 96 h, indicating that the retention of CAT could realize persistent tumour hypoxia relief." (PMID 36277398, 2022). "Recently, in 2020, the development of PLGDA-based NPs containing SAHA and catalase (a biological peroxidase), using a double emulsion method, allowed to overcome the radiation resistance due to tumor microenvironments, including hypoxia and histone deacetylase (HDAC) overexpression." (PMID 35163980, 2022). "DDRi@CAT‐M1Exos had higher accumulation in tumor compared with free CAT and free DDRi, possibly resulting from the prolonged circulation time of engineered exosomes, and the passive tumor‐targeting ability derived from enhanced permeability and retention (EPR) effect." (PMID 35715382, 2022). "In cancer cells, CAT can be found in high concentrations in the plasma membrane and occasionally released in the extracellular matrix, and can act as a tumor suppressor and as a survival agent during tumor progression." (PMID 36034648, 2022). "The CAT gene encodes catalase, which induces the decomposition of the H2O2 generated by cancer cells to produce oxygen, thereby attenuating the hypoxia condition in the tumor microenvironment." (PMID 36193154, 2022). "CAT generates oxygen in situ but may be degraded in vivo due to the upregulated protease in the tumor." (PMID 36873299, 2022). "While the POD- and CAT-mimicking activities of MoSe2 promoted CDT via the conversion of tumor-rich H2O2 into hydroxyl radicals and molecular oxygen, Au could be activated with NIR light resulting in a very high photothermal conversion efficiency of 73%." (PMID 35740402, 2022). "The avoidance of H2O2 overproduction is likely to be the cause of no promotion of cancer cells when there is simultaneous overexpression of SOD2 and CAT both in vitro and in vivo and of tumor-preventive and tumor-suppressive effects in the case of the simultaneous overexpression of SOD2 and GPX1." (PMID 36552527, 2022). "The results showed that CAT could produce oxygen by catalyzing H2O2 to alleviate the tumor hypoxic state." (PMID 36145513, 2022). "In addition, the expression of PRDX2 and PRDX5 in the GPx2 KD tumor was increased by 1.3-fold (logFC = 0.4) and catalase by 1.2-fold (logFC = 0.27), whereas the expression of SOD2 was unchanged." (PMID 35193955, 2022). "In tumor cells, catalase activity is unregulated, resulting in accumulation of H2O2." (PMID 36505711, 2022). "After intravenous injection, the CAT@Pt (IV)-liposome can effectively accumulate in the tumor." (PMID 36147526, 2022). "Scholars have designed a variety of nanodelivery systems to enhance the blood oxygen content of tumor sites, including direct oxygen delivery (by hemoglobin or perfluorocarbons NPs), catalytic oxygen production strategies (catalase oxygen-producing nanodelivery system), and so on." (PMID 35372087, 2022).
tumor (continued). "Similarly, antioxidants like GSH and catalase levels were found to be higher in normal and tumor control animals." (PMID 35197512, 2022). "Such functions were further determined by multiple experiments in vivo (i.e., subcutaneous tumour formation in nude mice) and in vitro (e.g., cell cloning, infection, migration, wound healing, cell cycle, apoptosis, CAT enzymatic activity, and intracellular GSH levels)." (PMID 36142252, 2022). "In contrast, obtaining tumor material from miRNAs is more complex, but the tumor‐expressed miRNA profile may better elucidate which tumor‐intrinsic pathways contribute to CAT." (PMID 35794963, 2022). "In contrast, increased catalase (CAT) can protect the tumor cell from excess ROS." (PMID 35745733, 2022). "For example, some strategies for relieving tumor hypoxia could be combined, such as delivering O2-loading nanocarriers into tumor cells to supplementary, employing some enzymes with catalase activities, gene slicing technology, and so on." (PMID 35211255, 2022). "EB could dissolve the cell membrane of E. coli carrying catalase under light exposure, and then the released catalase could generate oxygen to improve hypoxia in the tumor." (PMID 35711646, 2022). "Additionally, the GOD-mimetic activity of Au nanoparticles has been reported to be synergized with CAT-mimetic nanomaterial enhanced tumor therapy efficiency." (PMID 35193573, 2022). "Especially, CAT-mimic nano-enzyme enables activating the matrix metalloproteinases in the tumor tissue, which could lead to inflammation and even tumor metastasis." (PMID 36873299, 2022). "Inhibition of membrane-associated catalase abrogates the decomposition of H2O2 and, therefore, leads to the onset of HOCl signaling, as well as to a strong aquaporin-mediated influx of H2O2 into the tumor cells." (PMID 34679719, 2021). "The LMM@BSA clay nanosheets were used to efficiently load the photosensitizer Ce6, which could play the synergism with the catalase-mimic capacity of LMM@BSA to enhance the tumor PDT efficiency." (PMID 33536031, 2021). "However, although the tumor killing effect was forestalled by the addition of catalase, this protective effect disappeared with longer exposures (96h), suggesting an additional, oxidant-independent mechanism of VitC." (PMID 34899716, 2021). "Besides, the expression of CAT in tumor cells is lower than in normal cells, the increasing CAT level in tumor cells may cause changes in the activities of other peroxidases, which may also affect the level of ROS in tumor cells and promoting tumor cell invasion and spreading." (PMID 34277702, 2021). "Moreover, the inactivation of membrane-associated catalase could lead to the generation of more secondary singlet oxygen, which would inactivate the membrane-associated catalases on the neighbouring cells and result in auto-amplificatory process spreading in the tumour." (PMID 34299530, 2021). "Au@MnO2-PEG, using the Au core, functioned as a RT sensitizer and MnO2 shell as CAT mimics that mediate the decomposed H2O2 could not only overcome tumor hypoxia but also enhance the tumor sensitivity to RT." (PMID 34737942, 2021). "The lowest activity of catalase enzyme was reported in tumor tissues." (PMID 34096454, 2021). "Thus, H2O2 and ONOO− derived from free tumor cells massively generate secondary 1O2, followed by CAT inactivation and consequently HOCl signaling activation." (PMID 33477494, 2021). "Our data from a phase I clinical trial suggest that catalase levels in the primary tumor may play a role in the response to P-AscH− radio-sensitization." (PMID 33923601, 2021). "Although catalase abrogates the tumor cell killing of cancer cells indicative for a central role of hydrogen peroxide in this process, the pro-tumor neutrophils also produce ROS, suggesting that additional signals are required for anti-tumor activity, such as TRAIL and FasL." (PMID 34572138, 2021).
tumor (continued). "Therefore, FIGs-LC with the LOx-CAT cascade system can catalyze the excess lactate substrate to H2O2 intermediate in the tumor hypoxia condition for GSH-activated CDT." (PMID 34475406, 2021). "In addition, a proportional decrease in enzymatic antioxidants (catalase) was noticed in tumor lysates from groups treated with LCL-SIM (P < 0.05), LCL-DMXAA (P < 0.01) and the liposomal combination therapy (P < 0.05)." (PMID 34764332, 2021). "Indeed, targeting catalase to the mitochondrial matrix of tumour cells suppressed tumour progression and metastasis in invasive breast cancer in mice." (PMID 33803273, 2021). "On the other hand, the PtPB nanozyme is endowed with superior CAT and SOD-like catalytic activities by Pt doped with PB nanotubes, which contributed to the relieved inflammation caused by PTT, along with significant tumor inhibition." (PMID 34737942, 2021). "Thus, these CAT-CAR T cells can maintain their anti-tumor function and were shown to have a reduced oxidative state with decreased levels in ROS accumulation in solid human tumor samples." (PMID 33807867, 2021). "Moreover, catalase was mis-localized into cytoplasm in all tumor entities in comparison to the healthy tissue." (PMID 34360635, 2021). "Upon light excitation, encapsulated ICG results in simultaneous PAI and PDT of in vivo tumor tissues, while the catalase molecules catalyze the decomposition of endogenous H2O2 into O2 bubbles to intensify US imaging signal and enhance PDT efficacy simultaneously." (PMID 34522227, 2021). "Altered expression levels of CAT have been reported in tumor tissues." (PMID 34943091, 2021). "In vivo results demonstrated that the combined treatment of CAT@liposome and H2O2@liposome could promote tumor oxygenation, which further reversed the polarization of immune-supportive M1-type tumor-associated macrophages (TAMs)." (PMID 34452113, 2021). "Thus, the approach of introducing dual natural GOD and CAT enzymes into the tumor site for rapid glucose exhaustion and oxygen generation will be highly preferred for augmenting SDT." (PMID 34195614, 2021). "Hence, specific targeting of exogenous CAT to tumor hypoxic zone has been widely explored in recent years." (PMID 34277702, 2021). "The bystander effect on signalling between treated and untreated tumour cells (possibly within tumours) depends on the generation of secondary singlet oxygen by the treated cells and singlet oxygen-mediated catalase inactivation of the untreated recipient cells." (PMID 33801451, 2021). "Inspired by this biochemical pathway, we demonstrate the reactive oxygen species (ROS) induced tumor therapy by integrating lactate oxidase (LOx) and catalase (CAT) into Fe3O4 nanoparticle/indocyanine green (ICG) co-loaded hybrid nanogels (designated as FIGs-LC)." (PMID 34475406, 2021). "Catalase could protect tumour cells against specific apoptosis induction by inhibiting the intercellular ROS generation." (PMID 34630071, 2021). "It seems appropriate that additional branches of signaling chemistry that were elucidated in this way might later be tested for relevance in other tumor cell systems that are also defined by the classical NOX1/catalase connection." (PMID 34679719, 2021). "Therefore, PDT efficiency can be increased by increasing oxygen supply to tumor tissues, such as using perfluorocarbon and hemoglobin to deliver oxygen to tumor sites, or using catalase to decompose H2O2 produced by tumor cells to obtain O2." (PMID 34733821, 2021). "The data obtained so far indicate that intercellular apoptosis-inducing signaling of tumor cells after inhibition of their protective catalase seemed to require an influx of H2O2 through aquaporins to sensitize the cells to the apoptosis-inducing effect of signaling-derived hydroxyl radicals." (PMID 34679719, 2021).